DNAJC1 (DnaJ heat shock protein family (Hsp40) member C1)
Description:
May modulate protein synthesis.
Synonyms: HTJ1; DNAJL1; ERdj1; MTJ1
Tractability: Antibody: UniProt predicts a signal peptide or a membrane-spanning region; its Gene Ontology location is reachable by antibodies, with medium confidence. PROTAC: ubiquitination databases record sites on it; its protein half-life has been measured.
Gene: Protein-coding gene on chromosome 10 (21,756,538 to 22,003,769, reverse strand). Ensembl gene ENSG00000136770.
Subcellular location: Endoplasmic reticulum membrane; Nucleus membrane; Microsome membrane
Subcellular location (Human Protein Atlas): Endoplasmic reticulum
Gene Ontology:
Molecular function: protein binding; ATPase activator activity; protein-folding chaperone binding
Biological process: regulation of protein secretion; negative regulation of proteolysis; regulation of protein metabolic process
Cellular component: membrane; endomembrane system; endoplasmic reticulum; endoplasmic reticulum membrane; nuclear membrane; plasma membrane
Genetic constraint (gnomAD): Loss-of-function variants: 35 observed, 48.3 expected, observed/expected ratio (o/e) 0.72, 90% interval 0.55 to 0.96. The upper end of that interval is the gene's LOEUF score, 0.96, which puts it in group 4 of 6, group 1 being the genes least tolerant of losing a copy. Missense variants: 530 observed, 518.91 expected, observed/expected ratio (o/e) 1.02, 90% interval 0.95 to 1.1. Synonymous variants: 207 observed, 202.53 expected, observed/expected ratio (o/e) 1.02, 90% interval 0.91 to 1.15.
Homologues: Orthologues: chimpanzee DNAJC1 (99% identical), macaque DNAJC1 (96% identical), dog DNAJC1 (88% identical), pig DNAJC1 (86% identical), mouse Dnajc1 (85% identical), rat Dnajc1 (85% identical), rabbit DNAJC1 (84% identical), guinea pig DNAJC1 (80% identical), tropical clawed frog dnajc1 (65% identical), zebrafish dnajc1 (58% identical), Drosophila melanogaster CG7556 (30% identical), Caenorhabditis elegans dnj-2 (9% identical), and 3 more. Paralogues in human: DNAJC13 (21% identical), DNAJC2 (19% identical), DNAJC10 (16% identical), DNAJC14 (14% identical), DNAJC16 (13% identical), DNAJC21 (13% identical), DNAJC11 (12% identical), DNAJC25 (12% identical), DNAJC17 (11% identical), DNAJC3 (11% identical), DNAJC7 (9% identical), DNAJC18 (9% identical), and 8 more.
Diseases named in the same sentence as DNAJC1 in open-access papers:
DNAJC1 is named in the same sentence as 20 diseases in open-access papers, as found by Europe PMC text mining. Sharing a sentence is not in itself a finding about the gene and the disease. The quoted sentences say what the papers report.
breast carcinoma (3 papers, 2021 to 2025). "For example, DNAJC1 and OLA1 (which interacts with BRCA1) have been linked to breast cancer in cancer GWAS studies." (PMID 39535534, 2024). "This solution was also enriched in genes known to be associated with breast cancer susceptibility (BLM, CASP8, CASP10, DNAJC1, FGFR2, MRPS30, and SLC4A7, P-value = 3 × 10−4)." (PMID 33735170, 2021).
leukemia (2 papers, 2021 to 2024). A malignant (clonal) hematologic disorder, involving hematopoietic stem cells and characterized by the presence of primitive or atypical myeloid or lymphoid cells in the bone marrow and the blood. "Overexpression of DNAJC1 has been associated with tumor growth and invasiveness in leukemia and melanoma, suggesting a potential role in tumorigenesis." (PMID 38909166, 2024). "Despite its known involvement in regulating leukemia and melanoma, the function and mechanism of DNAJC1 in GBM remain poorly understood." (PMID 38909166, 2024). "In addition, we identified genes of previously unknown cancer relevance with regards to leukemia circulation (e.g., LRIF1, DNAJC1, and CMC2) and therapeutic treatment (e.g., EBPL, MESDC2, ZRANB2, GTF2A2)." (PMID 34764253, 2021).
liver cancer (2 papers, 2021 to 2023). An epithelial or non-epithelial malignant neoplasm that arises from the liver. "Quantitative real-time PCR and Western blotting were used to verify DNAJC1 expression in liver cancer cell lines." (PMID 37520264, 2023). "Several homologs of the Hsp40/DnaJ protein family (DnaJB6, DnaJC1, DnaJC5, DnaJC7, and DnaJC21) have been identified as unfavorable prognostic markers in liver cancer." (PMID 34356495, 2021). "Furthermore, immunohistochemical (IHC) was used to detect DNAJC1 expression in liver cancer tissues." (PMID 37520264, 2023).
osteosarcoma (2 papers, 2023 to 2024). A usually aggressive malignant bone-forming mesenchymal neoplasm, predominantly affecting adolescents and young adults. "In contrast, elevated HSPD1 and DNAJC1 expression were associated with inferior outcomes in osteosarcoma." (PMID 39430254, 2024). "More interestingly, the expression of several of these genes, including CHST13, FKBP11, SGMS2, TRPS1, PRKX, SP7, and DNAJC1, were highly associated with osteosarcoma prognosis." (PMID 37457661, 2023).
anaplastic astrocytoma (1 paper, 2024). "Our results demonstrated a gradual increase in DNAJC1 expression from normal cerebral cortex to astrocytoma (WHO grade II) or oligoastrocytoma (WHO grade II), and further to anaplastic astrocytoma (WHO grade III) and anaplastic oligodendroglioma (WHO grade III)." (PMID 38909166, 2024).
astrocytoma (1 paper, 2024). "Notably, GBM showed higher levels of DNAJC1 expression compared to less malignant subtypes such as astrocytoma, oligoastrocytoma, and oligodendroglioma." (PMID 38909166, 2024).
glioma (1 paper, 2024). A benign or malignant brain and spinal cord tumor that arises from glial cells (astrocytes, oligodendrocytes, ependymal cells). "In our research, we found that elevated DNAJC1 expression is positively associated with the infiltration of macrophages, neutrophils, and Th2 cells into the glioma TME." (PMID 38909166, 2024). "To further evaluate the expression pattern of DNAJC1 in different glioma grades, we performed immunohistochemical staining on tissue samples obtained from patients with various tumor grades as well as normal brain tissue samples." (PMID 38909166, 2024). "Our study, through a blend of bioinformatic inquiry and clinical data, contributes to a nuanced understanding of DNAJC1’s function in gliomas." (PMID 38909166, 2024). "Overall, our research underscores DNAJC1’s pivotal role in glioma pathogenesis and underscores its potential as a significant prognostic biomarker and a candidate for targeted therapy, opening new pathways for advancing glioma diagnostics and treatment." (PMID 38909166, 2024).
thyroiditis (1 paper, 2020). Inflammation of the thyroid gland. "Under Bonferroni significance (P < 1.1 × 10−3), we identified rs56186224, a variant located in an enhancer linked to both COMMD3 and DNAJC1, to be associated with self-reported thyroiditis (P = 4.2 × 10−4)." (PMID 32371927, 2020). "Furthermore, we find an association between helper T cell content in thyroid tissue and a COMMD3/DNAJC1 regulatory variant (P = 7.5 × 10−10), which is associated with thyroiditis in other cohorts." (PMID 32371927, 2020).
cancer (6 papers, 2020 to 2025). A tumor composed of atypical neoplastic, often pleomorphic cells that invade other tissues. "DNAJC1 was upregulated in most malignant tumors (including HCC) and may be involved in cancer initiation and development." (PMID 39430254, 2024).
tumor (4 papers, 2017 to 2024). "Our analysis revealed a significant upregulation of DNAJC1 in 20 different tumor types, including GBM and brain lower-grade glioma (LGG), compared to adjacent normal tissues." (PMID 38909166, 2024). "Further examination of TCGA, CGGA, and GEO databases corroborated the elevated expression of DNAJC1 in GBM tissues, which increased concomitantly with higher WHO tumor grades." (PMID 38909166, 2024). "The gene was significantly upregulated in at least 20 tumor subtypes, with notably high levels in GBM or LGG, suggesting a potential oncogenic role for DNAJC1." (PMID 38909166, 2024). "The DNAJC1 and TSC22D2 genes were related to a large number of genes to suppress cell proliferation in tumor processes and adverse conditions." (PMID 35629975, 2022).
DNAJC1 also shares sentences with these, for which no sentence is quoted: hepatocellular carcinoma (2 papers); melanoma (2); anaplastic oligodendroglioma (1); asthma (1); glioblastoma (1); metabolic disorders (1); Obesity (1); oligoastrocytoma (1); oligodendroglioma (1); prostate carcinoma (1).